RN7SL764P (RNA, 7SL, cytoplasmic 764, pseudogene)
Gene: Miscellaneous RNA gene on chromosome 2 (219,102,434 to 219,102,719, forward strand). Ensembl gene ENSG00000240317.
Homologues: Orthologues: chimpanzee Metazoa_SRP (98% identical), macaque Metazoa_SRP (88% identical). Paralogues in human: RN7SL1 (86% identical), RN7SL2 (86% identical), RN7SL3 (85% identical), RN7SL408P (83% identical), RN7SL145P (83% identical), RN7SL296P (83% identical), RN7SL45P (82% identical), RN7SL14P (82% identical), RN7SL448P (82% identical), RN7SL679P (82% identical), RN7SL147P (81% identical), RN7SL478P (81% identical), and 705 more.